IL13 (interleukin 13)
Diseases named in the same sentence as IL13 in open-access papers (continued):
Sharing a sentence is not in itself a finding about the gene and the disease.
minimal change disease (5 papers, 2010 to 2025). "It is possible that IL-13, a known stimulator of the IgE response, may mediate proteinuria in patients with minimal change disease by directly inducing CD80 expression in the podocyte." (PMID 28035995, 2016).
peanut allergy (5 papers, 2012 to 2025). "A blockade of IL-4/IL-13 signaling can suppress IgE production and Th2 cytokine responses in a mouse model of peanut allergy." (PMID 40005151, 2025). "In vitro, allergen-stimulated T cells and T-cell clones generated from patients with peanut allergy produced increased levels of the type 2 cytokines IL-4, IL-5, and IL-13." (PMID 32497050, 2020). "The type 2 cytokines, IL-4 and IL-13, play critical roles in IgE-mediated intestinal peanut allergy in humans and mice." (PMID 32497050, 2020). "In both humans and mice, the type 2 cytokines, IL-4 and IL-13, play critical roles in the development of IgE-mediated intestinal peanut allergy." (PMID 32497050, 2020). "In the presence of H. polygyrus, the peanut antigen-specific IL-13 levels were drastically reduced, and these dampened IL-13 levels along with protection from peanut allergy were lost when mice were treated with neutralizing IL-10 antibody." (PMID 23053394, 2012). "Peanut allergy in humans is Th2-dependent, during sensitization to peanut, priming of allergen-specific Th2 cells results in the production of Th2 cytokines (such as IL-4 and IL-13), which are responsible for class switching by B cells, allowing IgE production." (PMID 30988664, 2019).
peritonitis (5 papers, 2020 to 2023). Inflammation of the peritoneum (tissue that lines the abdominal wall and covers most of the organs in the abdomen). "Previous studies suggest that IL-4 and IL-13, two cytokines known to induce STAT6 activation, are not involved in STAT6 phosphorylation during zymosan-induced peritonitis." (PMID 35327639, 2022). "However, in the present study, we found that, similar to IL-4 and IL-13, the TSG6 mRNA and/or protein levels remained the same in PLF, peritoneal macrophages, and spleen after zymosan injection, indicating that TSG6 is not involved in the STAT6 pathway during zymosan-induced peritonitis." (PMID 35327639, 2022).
preeclampsia (5 papers, 2018 to 2025). Preeclampsia is a hypertensive disorder of pregnancy that is characterized by new-onset hypertension with proteinuria presenting after 20 weeks of gestation, and depending on mild or severe forms may initially present with severe headache, visual disturbances, and hyperreflexia. "Although the current report revealed the genetic association between rs2069740(T/A) and rs34255686(C/A) polymorphisms in the IL-13 gene and the risk of preeclampsia, a more significant sample size is required to validate the observations of the present study." (PMID 37238928, 2023). "So, due to these observed significant differences, rs2069740(T/A) and rs34255686(C/A) polymorphisms of IL-13 were considered relevant with an increased risk of preeclampsia." (PMID 37238928, 2023). "Though very little is known about the IL‐13 gene polymorphism on the development of preeclampsia, the impact of several other polymorphic sites have been reported." (PMID 38057745, 2023). "This study was aimed to discover association between interleukin-13 (rs20541, and rs56035208) and interleukin-19 (rs1028181 (T/C) and rs2243191(T/C)) polymorphisms with susceptibility to preeclampsia." (PMID 38057745, 2023). "We also concluded that polymorphisms of IL-13 in the positions of rs2069740(T/A) and rs34255686(C/A) contribute to the risk of preeclampsia." (PMID 37238928, 2023). "Similarly, overweight and obese pregnant women with gestational hypertension show increased IL-13 concentration, which in turn is associated with elevated triglyceride levels." (PMID 29675435, 2018). "The present study aimed to examine the interleukin-13 and interleukin-4 pathway potential in the early detection of preeclampsia as well as the relationship between interleukin-13 rs2069740(T/A) and rs34255686(C/A) polymorphisms and preeclampsia risk to present a combined model." (PMID 37238928, 2023). "Therefore, the present study aimed to study the relationship between preeclampsia risk and rs2069740 (T to A exchange) and rs34255686 (C to A exchange) polymorphisms of IL-13 while evaluating the expression patterns of IL-13 and IL-4 pathway genes in this disease." (PMID 37238928, 2023). "IL-4 and IL-13 pathways can considerably affect preeclampsia and deep learning models based on these pathway genes predicting patients’ status with high accuracy." (PMID 37238928, 2023). "This study applied the second method and used two deep learning algorithms to diagnose preeclampsia based on IL-4 and IL-13 pathway expression patterns." (PMID 37238928, 2023). "The outcomes revealed that the expression levels of interleukin-4 and interleukin-13 pathway genes could significantly differentiate early preeclampsia from normal pregnancy." (PMID 37238928, 2023). "The results revealed that none of the allele or genotype frequencies of IL-13 rs20541 (G/A) and rs56035208 (G/C) polymorphisms had any significant association with preeclampsia susceptibility." (PMID 38057745, 2023). "However, almost none of them directly mentioned the IL-13 and IL-4 signaling pathway; they suggested the genes connected to this pathway as being preeclampsia risk factors, initiators or progressors." (PMID 37238928, 2023). "No risk of preeclampsia was found in all comparisons for interleukin-13 polymorphisms." (PMID 38057745, 2023). "On the other hand, the role of interleukin-13 (IL-13) and interleukin-4 (IL-4) pathway-related genes, such as STAT1, SOCS1 and JAK, in preeclampsia has been investigated." (PMID 37238928, 2023).
psoriasis vulgaris (5 papers, 2017 to 2025). Plaque psoriasis is the most common presentation of psoriasis. "Pre-selected SNP sets were associated with psoriasis vulgaris analysis, which was used to identify four SNP-associated targeted therapy efficiencies: IL1β (rs1143633), IL4 (IL13) (rs20541), IL23R (rs2201841), and TNFα (rs1800629) genes." (PMID 33383665, 2020). "Studies found that the increased Th2 and Th17 immune response may play a role in EP pathogenesis, endorsed by the higher serum level of interleukin (IL)-13, IL-4, IL-6 and IL-10 in EP patients than patients with plaque psoriasis." (PMID 34970217, 2021). "Moreover, miR-143 can suppress IL-13 expression in human mast cells, and so it is hypothesized that miR-143 may be involved in progression of psoriasis vulgaris via regulating IL-13 expression." (PMID 28881648, 2017).
respiratory failure (5 papers, 2021 to 2025). The significant impairment of gas exchange within the lungs resulting in hypoxia, hypercarbia, or both, to the extent that organ tissue perfusion is severely compromised. "Prostaglandin D2-stimulated IL-13 production is associated with respiratory failure, possibly due to hyaluronan accumulation in the lungs." (PMID 35935851, 2022). "Moreover, COVID‐19 ARDS is associated with proinflammatory lipid mediators including prostaglandin D2 (PGD2), which produces IL‐13 and is associated with respiratory failure." (PMID 40170544, 2025).
rosacea (5 papers, 2018 to 2025). A chronic erythematous skin disorder that affects the face. "IL-4 and IL-13, although classically linked to Th2 responses, have also been detected in rosacea lesions and contribute to chronic inflammation and fibrosis." (PMID 40725084, 2025). "The associations of rosacea with the IL13, IRF4 and HLA gene regions are consistent with the known inflammatory component of the disease." (PMID 29771307, 2018). "Proinflammatory cytokines and chemokines: Another GWAS study of Caucasian rosacea patients found SNP in genes such as interleukin-13 (IL-13) and interferon regulatory factor-4 (IRF4)." (PMID 39136023, 2024). "Future studies will be necessary in order to assess specific risk factors and the mechanism responsible for the development of rosacea-like folliculitis in a subset of patients following IL-4/IL-13 inhibition." (PMID 32344789, 2020). "The most significant variant observed within the fifth locus is an intronic SNP (rs847) within the interleukin 13 (IL13) gene, with the minor allele (T) strongly associated with less severe forms of rosacea (P = 2.8 × 10−9)." (PMID 29771307, 2018). "Gene expression quantification revealed an upregulation of inflammatory cytokines IL-33, IL-13, MCP-1, and IL-1ß that have been identified in the pathogenesis of rosacea." (PMID 41296102, 2025). "Collectively, the HLA, IL13 and IRF4 findings highlight the critical role of immune modulation and rosacea disease pathology." (PMID 29771307, 2018). "Furthermore, gene expression analysis revealed elevated levels of inflammatory cytokines IL-13, IL-33, MCP-1, IL-1β, and TNF-α in LL-37-treated mice, consistent with rosacea’s symptoms and serum MCP-1 level." (PMID 41296102, 2025).
sarcoma (5 papers, 2013 to 2023). A usually aggressive malignant neoplasm of the soft tissue or bone. "These ROR1 CAR-T cells were effective against sarcoma cells as evidenced by the synthesis of high levels of IFN-γ, TNF-α, and IL-13 in cocultures with sarcoma cell lines and the ability to reduce the tumor growth in a murine osteosarcoma xenograft model." (PMID 36873868, 2023). "Second, SB modified CAR T cells derived from healthy donors and sarcoma patients targeting IGF1R or ROR1 displayed a specific cytotoxicity and released predominantly IFN-γ, TNF-α and IL-13 cytokines against sarcomas in vitro." (PMID 26173023, 2015). "It is also reported that IL-13 involved in the IL-4R-STAT6 pathway, are necessary for tumor promotion in 15-12RM sarcoma model." (PMID 26993600, 2016). "IGF1R and ROR1 CAR T cells derived from eight healthy donors using the Sleeping Beauty (SB) transposon system were cytotoxic against sarcoma cells and produced high levels of IFN-γ, TNF-α and IL-13 in an antigen-specific manner." (PMID 26173023, 2015). "The primary tumor cultures seem to have an intermediate expression of IL-13Rα2 where the IC50 for these cells is similar to the murine sarcoma cell line MCA304, which has moderate sensitivity to IL-13-PE." (PMID 23421960, 2013).
T-cell lymphoma (5 papers, 2018 to 2024). "A previous preclinical study in mice found IL13 to inhibit the development of T-cell lymphoma and ovarian adenocarcinoma; this appeared to be facilitated by converting tumor-supporting macrophages to cytotoxic effectors." (PMID 35011853, 2021). "We first revealed that IL-13 promoted NK/T-cell lymphoma cells chemotherapy resistance to adriamycin (ADM) by increasing ABCC4 expression." (PMID 30643796, 2018). "Our findings concluded that IL-13 inhibited chemotherapy sensitivity of NK/T-cell lymphoma cells by regulating ABCC4, disrupting which may effectively improve the therapy protocols against resistant NK/T-cell lymphoma." (PMID 30643796, 2018). "IL-13 promoted the expression of ABCC4, leading to increased resistance of NK/T-cell lymphoma cells to asparaginase." (PMID 38365716, 2024).
Type I hypersensitivity reaction (5 papers, 2020 to 2024). "IL18 induces an increase in the serum concentrations of IgE, IL4, and IL13, which are characteristic cytokines of hypersensitivity type 1." (PMID 33255937, 2020). "In type I hypersensitivity reactions, low concentrations of the allergen (via inhalation or exposure in the gastrointestinal tract) presented in the presence of interleukin (IL)-4, IL-5, IL-9, and IL-13 are responsible for the dominant Th2 response." (PMID 34099042, 2021).
allergic contact dermatitis (4 papers, 2012 to 2026). An inflammatory skin condition caused by an immune response to direct contact between the skin and an allergen. "Among the cytokines whose levels increased with worsening of Allergic contact dermatitis, a significant increase in the expression of Il4 and Il13 was observed." (PMID 41488203, 2026). "In addition, IL-31 mRNA expression was also increased in skin samples of patients with allergic contact dermatitis and was correlated with IL-4 and IL-13 levels." (PMID 22853438, 2012).
autism spectrum disorder (4 papers, 2012 to 2026). A spectrum of developmental disorders that includes autism, and Asperger syndrome. "One clinical trial found reductions in the production of IL-13 and a decrease in the frequency of CD8+ T cells expressing TNF-α in the group of children with autism spectrum disorder (ASD) after they received treatment with BC products." (PMID 37834178, 2023).
B cell lymphoma (4 papers, 2012 to 2024). "Interestingly, our findings demonstrated the critical roles of Nlp in B cell development through affecting levels of interleukin-13,17 and 21 secreted by immune cells, and Nlp deficiency mice were prone to B cell lymphoma." (PMID 38904019, 2024). "Moreover, Nlp deficient mice were prone to spontaneous B cell lymphoma, since the developments and functions of lymphocytes significantly depended on secretory proteins through ER-to-Golgi vesicle trafficking, including IL-13, IL-17 and IL-21." (PMID 38904019, 2024). "A previous study showed dysregulated circulating cytokines (such as IL5, IL13, TNF, etc.)were correlated with B-cell non-Hodgkin lymphoma." (PMID 35452413, 2022).
brain injury (4 papers, 2021 to 2026). Acute and chronic (see also brain INJURIES, CHRONIC) injuries to the brain, including the cerebral hemispheres, CEREBELLUM, and brain STEM. "We demonstrate that increased IL-13 is a hallmark of traumatic brain injury (TBI) in male mice as well as in two distinct cohorts of human patients." (PMID 36639371, 2023). "After a single mild traumatic brain injury, interleukin-10, interleukin-13, interleukin-4 and tumour necrosis factor-alpha were elevated 3 days post-injury while interleukin-10 and tumour necrosis factor-alpha levels were elevated 14-days post-injury." (PMID 41675431, 2026).
cardiomyopathy (4 papers, 2012 to 2021). A disease of the heart muscle or myocardium proper. "Furthermore, IL-13 knockout mice exhibit severe cardiomyopathy, impaired cardiac function, and HF." (PMID 23226928, 2012).
central obesity (4 papers, 2015 to 2022). "Interestingly, it has been recently shown that increased central obesity and body weight are associated with elevation in the circulating levels of IL-13." (PMID 29675435, 2018). "Looking specifically at central obesity, higher levels of IL-5, IL-6, IL-12, IL-13, and IFN-γ were reported in participants with abdominal obesity compared to those without." (PMID 36364892, 2022). "After Bonferroni-correction, IL-5, IL-12 and IL-13 were found to be elevated in both general and central obesity, and IL-10 elevated in the central obese." (PMID 25781614, 2015). "General obesity was associated with significantly elevated levels of IL-5, IL-10, IL-12, IL-13, IFN-γ and TNF-α, central obesity with significantly elevated IL-5, IL-10, IL-12, IL-13 and IFN-γ-levels." (PMID 25781614, 2015). "Among the tested cytokines, IL-5, IL-10, IL-12, IL-13 and IFN-γ were elevated in both general and central obesity." (PMID 25781614, 2015). "In the post-hoc ANOVA, subjects with central obesity showed significantly elevated serum concentrations of IL-5, IL-10, IL-12, IL-13 and IFN-γ compared to the group without central obesity (after Bonferroni correction, differences remained significant for all but IFN-γ)." (PMID 25781614, 2015). "Looking specifically at central obesity, we found higher levels of IL-5, IL-10, IL-12 and IL-13 and IFN-γ in participants with compared to those without central obesity." (PMID 25781614, 2015).
cerebral malaria (4 papers, 2012 to 2017). A sequestration of Plasmodium falciparum in the brain, which can cause coma and/or seizures. "In this study, carriage of the rs20541C>T polymorphism was associated with increased risk of developing cerebral malaria; this polymorphism introduces a nonsynonymous change in exon 4 of the gene encoding IL-13." (PMID 23144702, 2012). "SNPs in the genes encoding IL-13 and reticulon-3 (RTN3) were associated with increased risk of cerebral malaria." (PMID 23144702, 2012). "In contrast, anti-inflammatory cytokines (produced by cells that include monocytes and Th2 cells) such as IL-10 and IL-13 have been shown to downregulate the production of proinflammatory cytokines and to reduce the incidence of experimental cerebral malaria (ECM) in mouse models." (PMID 28122790, 2017).
cholestasis (4 papers, 2019 to 2023). Impairment of the bile flow caused by obstruction within the liver, or outside the liver in the bile duct system. "On the other hand, IL-13 was associated with biliary fibrosis, diarrhea, and perianal inflammation in a genetic model of cholestasis, ABCB4-knockout mice." (PMID 37629063, 2023). "Furthermore, an IL13 knockout improved/normalized the intestinal microbiome, which is thought to be directly linked to improved barrier function and reduced cholestasis." (PMID 37629063, 2023). "In this murine model of cholestasis, we were able to achieve a significant improvement in liver integrity with a global IL13 knockout, at least in this specific animal model." (PMID 37629063, 2023). "Abcb4−/− mice devoid of IL-13 transiently improved cholestasis and converted the composition of the gut microbiota towards healthy conditions." (PMID 32846954, 2020). "Our study revealed that BA livers had significant higher expression levels of TGF-β1 and IL-13 compared to the cholestasis control." (PMID 31632941, 2019). "In our model, the impact of ER-stress on hepatocyte damage during cholestasis is shown by the phosphorylation of ER-stress-dependent PERK and eIF2α in Abcb4−/− mice, which was reduced by the IL-13−/−-knockout." (PMID 32846954, 2020). "In conclusion, our study showed that compared to cholestasis controls, IL-33 and ST2 receptor expressions are significantly increased in BA livers; their interaction can induce the overexpression of downstream cytokines TGF-β1 and IL-13." (PMID 31632941, 2019). "Lack of IL-13 protected Abcb4−/− mice transiently from cholestasis." (PMID 32846954, 2020).
Chronic colitis (4 papers, 2010 to 2020). A chronic inflammatory disease of the large intestine (colon, cecum and rectum). "The level of IL-13 was noticeably increased with anti-CD3 and anti-CD28 mAb stimulation, and similar results were observed without any stimulation in the supernatants of the MLN of the IL-33-treated chronic colitis group compared with the control group." (PMID 30539029, 2018). "In wt mice with chronic colitis, IL-23a, IL-13, NF-kB2, PTGS1, SMAD3 and SMAD7 (P≤0.05) were significantly down-regulated, with the largest variations affecting the expression of IL-23a and IL-13 (100- and 10-fold)." (PMID 20706593, 2010).